INS (insulin)
Diseases named in the same sentence as INS in open-access papers (continued):
Sharing a sentence is not in itself a finding about the gene and the disease.
Obesity (continued). "During lactation, male and female offspring developed early obesity characterized by increase of body weight and adiposity at weaning in parallel to increased glycemia and insulin levels." (PMID 36926037, 2023). "The cardiometabolic effects of obesity on insulin sensitivity, inflammation, oxidative states, and subsequent increased CVD and mortality risk have been a frequent target of scientific research." (PMID 36890477, 2023). "The effects of IP-A and IP-B were mainly studied on postprandial blood glucose and peak insulin, and the outcome for obesity was just peripheral." (PMID 37764380, 2023). "Recent studies using the Sparc-KO mice reported impaired glucose homeostasis in aging and HFD-induced obesity with defects in insulin secretion from the pancreas." (PMID 37781916, 2023). "Individuals with obesity and MetS represented significantly higher levels of serum TC, TG, insulin, and iron, but lower uric acid values (P < 0.05 for all of them)." (PMID 37670399, 2023). "Murine models suggest that exercise in mothers with obesity prior to and during gestation improves maternal insulin resistance, reduces placental lipid deposition and improves insulin sensitivity in offspring." (PMID 37338777, 2023). "Another study has also suggested that obesity can increase the secretion of hormones responsible for controlling food intake and body weight, such as pancreatic amylin and insulin (in obese humans and rodents)." (PMID 37237272, 2023). "Obesity is a condition that is usually accompanied by a long list of metabolic ailments, including insulin resistance." (PMID 38132872, 2023). "In boys with obesity, postprandial insulin AUC negatively correlated with postprandial AUC plasma total ghrelin." (PMID 37287649, 2023). "Obesity due to overfeeding impedes glucose clearance by disrupting insulin signaling in the main metabolic organs, including the muscle and liver, which results in hyperglycemia." (PMID 36920656, 2023). "Individuals with double diabetes often have poorer glycemic control with increased insulin requirements, and components of the metabolic syndrome such as dyslipidemia, insulin resistance, obesity and hypertension." (PMID 36935526, 2023). "Obesity induces various metabolic dysfunctions and inflammatory processes that increase insulin, insulin-like growth factor, leptin, and interleukin-6, while decreasing adiponectin." (PMID 38013342, 2023). "Most patients with polycystic ovaries are characterized by abdominal fat accumulation or centripetal obesity, which eventually leads to decreased insulin sensitivity and androgenemia." (PMID 37111146, 2023). "BMI also plays a crucial role in miR-125b expression-regulated glucose metabolism: miR-125b knockout reduced insulin sensitivity and, consequently, glucose utilization in mice with high-fat diet-induced obesity." (PMID 38139235, 2023). "Brown fat is a special adipose tissue rich in mitochondria, and its activity is inversely correlated with obesity, blood glucose concentration, and insulin sensitivity." (PMID 36742427, 2023). "The factors that contribute to lower perceived HRQoL in Kuwait are being female, obesity (BMI ≥30), insulin usage, lower levels of education, and the presence of complications and/or comorbidities." (PMID 37033039, 2023). "Obesity-induced inflammatory activation is prevented in TLR4-deficient mice, and these mice also show resistance to insulin infusion-induced fat gain." (PMID 37346355, 2023). "SPEAR element activation in multiple cell types by IFN-γ, insulin, and spike suggest pathophysiological significance in the broader contexts of obesity and inflammation." (PMID 37296097, 2023). "Fenretinide prevented obesity, improved insulin sensitivity and completely inhibited hepatic triglyceride accumulation, ballooning and steatosis." (PMID 36894641, 2023).
Obesity (continued). "Deletion of the Dgat1 gene (Dgat1−/−) increased energy expenditure in mice, improved leptin and insulin sensitivity, and improved resistance to diet-induced obesity and NAFLD." (PMID 36817150, 2023). "As observed in the animal models, ALA exerted its anti-obesity effect by modulating oxidative stress, and inflammation and by increasing insulin sensitivity in the subcutaneous and visceral adipose tissue of high-fat diet rats." (PMID 37251328, 2023). "Because of these immune responses and disruptions in insulin signaling, obesity often leads to Metabolic Syndrome (MetS) and Type 2 Diabetes (T2D)." (PMID 40880838, 2023). "Further, a stepwise significant increase in leptin, insulin, serum glucose and a decrease in ghrelin was found in stage I and II obesity participants when compared with OW and LS." (PMID 38313840, 2023). "Some studies reported a (relative) decrease of Tregs in obesity-induced mice and in agreement with this the induction of Tregs improved insulin sensitivity." (PMID 37659013, 2023). "GF mice that lack any microbiome exhibit lower adiposity and higher insulin sensitivity despite greater food intake, and they are protected against diet-induced obesity." (PMID 37842639, 2023). "In metabolic regulation, deletion or inactivation of CEACAM1 impairs insulin clearance in mice, compromising metabolic homeostasis and promoting obesity, hepatic steatosis, and fibrosis." (PMID 36741860, 2023). "In mammals, carotenoids have been shown to lower blood concentrations of inflammation markers and pro-inflammatory cytokines, improve insulin sensitivity, and reduce obesity." (PMID 36909926, 2023). "IGF1 along with insulin was reported to activate the signaling cascade of differentiation of MSCs to adipogenic or osteoblastogenic pathways in patients with obesity and diabetes." (PMID 36831180, 2023). "The pathophysiology of OAMD stems from dysregulation of the insulin signalling pathway (insulin resistance [IR]) that is, in turn, driven by weight-gain and obesity." (PMID 37367914, 2023). "In contrast, baseline obesity and baseline use of sulfonylurea and insulin significantly reduced the likelihood of continuing dulaglutide." (PMID 37305431, 2023). "Skeletal muscle is responsible for >80% of insulin-stimulated glucose uptake that is attenuated by the inflammatory milieu of obesity and augmented by aerobic exercise." (PMID 37675469, 2023). "Probiotics given to pregnant women with GDM and/or obesity in controlled clinical studies decreased fasting glucose levels, increased insulin sensitivity and improved lipid metabolism compared to placebo treatment." (PMID 37998819, 2023). "The main disadvantage of the described diets is their failure to develop obesity and resistance to insulin, therefore, in recent years, other dietary patterns were designed permitting the reconstruction of all main aspects of NAFLD pathogenesis." (PMID 38434194, 2023). "Thiazolidinediones are PPARγ full agonists with potent insulin-sensitizing effects, whereas their oral usage is restricted because of unwanted side effects, including obesity and cardiovascular risks." (PMID 36841479, 2023). "The metabolic abnormalities connected with obesity can lead to the development of pathophysiological common conditions in humans, such as metabolic syndrome and insulin and leptin resistance (pathological status)." (PMID 38089973, 2023). "Investigating the relationship of DII with chronic diseases is mainly related to obesity since stimulating more insulin release results in increased body fat mass by decreasing fat oxidation and elevating carbohydrate oxidation." (PMID 37226148, 2023). "We searched for associations between BMI (measure of obesity), leptin (measure of adiposity), glucose, C-peptide and ISHOMA (measures of glucose-insulin metabolism) and circulating serum metabolites." (PMID 37029207, 2023). "Studies on SORT1 knockout mice have shown that they exhibit resistance to obesity and increased insulin sensitivity." (PMID 38082425, 2023).
Obesity (continued). "Obesity-related insulin and leptin resistance is reported in hypothalamus, together with neuroinflammation and gliosis." (PMID 36914703, 2023). "lncRNA H19 overexpression inhibits obesity, improves insulin sensitivity, and promotes mitochondrial biosynthesis." (PMID 37791070, 2023). "However, it has been demonstrated that a diet with high insulinemic potential, due to enhancing insulin secretion during a long period, can reduce fat oxidation and increase carbohydrate oxidation resulting in the development of fat mass and increasing the risk of obesity." (PMID 37582773, 2023). "Protein tyrosine phosphatase 1B (PTP1B) has been shown to be involved in the negative regulation of both insulin and leptin action and was suggested to play an important role in insulin signalling and possibly in obesity in humans." (PMID 37888445, 2023). "Obesity leads to enhanced circulating levels of insulin, IGF-I, IGF-II and IGF-binding proteins (IGFBP-3), while reducing levels of the low molecular weight IGF-binding proteins (IGFBP-1, IGFBP-2)." (PMID 38260836, 2023). "Patients with NAFLD and obesity had a higher incidence of hyperinsulinemia and higher median insulin and HOMA-IR values." (PMID 37724205, 2023). "Non-alcoholic fatty liver disease (NAFLD) is a common chronic liver pathology that strongly correlates to obesity and metabolic syndrome that are both characterized by insulin resistance of peripheral tissues." (PMID 36649358, 2023). "Omega-3 fatty acids have antioxidant, anti-inflammatory, anti-obesity, and insulin-sensitive properties." (PMID 38025704, 2023). "In adolescents with obesity, post-meal ClI declines during puberty transition along with reduced insulin sensitivity and increased insulin secretion." (PMID 37834412, 2023). "In individuals with obesity, adipocytes become resistant to insulin-stimulated inhibition of lipolysis." (PMID 37675136, 2023). "This was attributed to mitochondrial dysfunction in autophagy-deficient Macrophages, suggesting a critical role for macrophage autophagy in regulating adipose inflammation and insulin sensitivity in obesity." (PMID 37153549, 2023). "For example agonists of FXR and GPBAR1 can improve glucose and insulin sensitivity and increase energy metabolism which can prevent obesity and NAFLD." (PMID 37941122, 2023). "It has been shown that HIF-1 increases obesity-related inflammation, inhibits insulin signaling, and promotes angiogenesis." (PMID 37516743, 2023). "CB1R-KO mice are also resistant to obesity-accompanied changes in metabolic parameters, including hyperlipidemia and elevated plasma insulin and leptin levels that consequently appear in obese wild-type (WT) mice." (PMID 36830844, 2023). "Third, the repeated mention of obesity or overweight is undoubtedly related to impaired insulin secretion." (PMID 36936171, 2023). "Overall, individuals with a higher food processing score exhibit higher blood pressure, trunk fat, and subscapular skinfold, measures of obesity, blood insulin, and triglyceride levels; and lower “good” HDL cholesterol." (PMID 37085506, 2023). "For example, in murine, alteration in miR-30a-5p, miR-133a-5p, and miR-107-5p levels was observed in the early stages of obesity, leading to disturbances in adipokines, insulin, and glucose levels." (PMID 38003013, 2023). "Among obesity-related biomarkers, insulin was most strongly correlated with BMI, fat mass index, and percentage body fat, and showed decreasing correlations with age." (PMID 36859451, 2023). "Among these proteins, CRP showed the strongest association with BMI, which has also been associated with clinical parameters linked with obesity and PRAP1 showed a strong positive association with fasting insulin levels." (PMID 36717394, 2023). "Many studies with on-site visits targeting lifestyle behaviors in children with overweight and obesity have demonstrated improvements in glucose and insulin sensitivity." (PMID 37049618, 2023).
Obesity (continued). "Literature has long established that pathology arising from obesity and lipotoxic diets is a consequence of chronically impaired insulin signaling." (PMID 36839327, 2023). "Since the male PE offspring showed an increased postnatal weight gain, a subset of metabolic active obesity-related hormones, such as Ghrelin, Glucagon, Insulin, Leptin and PYY, were analyzed." (PMID 37108049, 2023). "Dysregulation of insulin signaling observed in obesity, metabolic syndrome, and T2DM extends to the brain and can be responsible for a broad spectrum of brain disorders." (PMID 37432552, 2023). "It is insulin response to an OGTT that identifies children with obesity suffering oxidative stress and inflammasome activation more specifically." (PMID 37599368, 2023). "Obesity also leads to hormonal imbalances, particularly insulin resistance, which can disrupt sleep–wake cycles and the appetite–satiety circuit." (PMID 38004130, 2023). "ATMs have been shown to negatively modulate insulin action via CD11c+ pro-inflammatory macrophages, indicating that pro-inflammatory macrophages are a target for the treatment of obesity-related insulin resistance." (PMID 37153549, 2023). "While circulating insulin concentrations tended to be increased commensurate with the obesity of these animals, glucose concentrations remained normal in ad libitum–fed animals and during an i.p. glucose tolerance test." (PMID 37581939, 2023). "A study on mice found that CRY1 deficiency had an interaction with the high-fat diet and can lead to increased obesity as a result of increased insulin and accumulation of fat in white adipose tissue." (PMID 37580741, 2023). "Very recently, a study documented that gallic acid improved insulin sensitivity; reduced obesity, blood pressure and cholesterol levels; however, also tempted adipogenesis in 3T3-L1 adipocytes." (PMID 37110767, 2023). "If obesity is present, the combination of basal insulin and GLP-1 RA titrated to the highest doses approved for weight loss should be considered." (PMID 37468901, 2023). "It had been reported that Mucinivorans not only alleviated obesity and improved insulin sensitivity in hosts, but also regulated lipid metabolism and inhibited cholesterol synthesis." (PMID 37689643, 2023). "High insulin levels in people with obesity and metabolic syndrome lead to low insulin sensitivity in the brain, decreased dopamine release after food intake, and consequently, an increased need to eat high-calorie, palatable foods." (PMID 37374323, 2023). "Insulin curves after glucose intake in the groups with obesity according to BF% were slightly higher than those of the NW group, but the differences were not statistically significant." (PMID 37667334, 2023). "THCV is a minor cannabinoid from C. sativa with evidence of medicinal properties in metabolism, nausea, obesity and insulin sensitivity, pain, and inflammation." (PMID 37834076, 2023). "loaded celastrol into BSA nanoparticles and produced Celastrol-BSA-NPs by high-pressure homogenization technology, which can reduce lipid accumulation and improve insulin sensitivity to treat diet-induced obesity." (PMID 36714199, 2023). "In children with obesity, differences in insulin curve morphology along oral glucose tolerance test (OGTT) also relate to metabolic complications." (PMID 37599368, 2023). "According to numerous authors, women with PCOS were characterized by an increased concentration of those adipokines, which further exacerbated the obesity-related disorders of tissue sensitivity to insulin." (PMID 37630842, 2023). "Exercise in children and adolescents with obesity can improve anthropometric (body mass, BMI, central obesity, fat mass) cardiovascular (triglycerides, fasting glucose, fasting insulin) parameters, and cardiorespiratory fitness." (PMID 37291604, 2023).
Obesity (continued). "It is well established that obesity promotes chronic low-grade inflammation due to the release of inflammatory factors and free fatty acids from adipose tissue, which alter the insulin signaling pathway in muscle cells." (PMID 37108574, 2023). "Recent studies have pointed towards exploring the possible regulatory roles of lncRNAs in obesity development and progression, and their effect on metabolic homeostasis, adipogenesis, and insulin function." (PMID 37104004, 2023). "Local diosmin administration in subcutaneous fat (inguinal white adipose tissue [iWAT]) improved insulin sensitivity and attenuated obesity via enhancing browning of white fat and energy expenditure." (PMID 36841479, 2023). "In the GLP1R gene, we found variants associated with dyslipidemia, resistance to liraglutide and exenatide, metabolic syndrome, insulin levels, BMI, glucose levels, and obesity, according to previously studies." (PMID 37888112, 2023). "For example, studies have shown that people with high levels of IGF-1 are more likely to develop resistance to insulin and overweight or obesity, both of which are hallmarks of metabolic syndrome." (PMID 38248733, 2023). "Formerly, several physiological roles of these organokines have been described in obesity, especially in the regulation of glucose and lipid metabolism, insulin sensitivity, oxidative stress and low-grade inflammation." (PMID 36837889, 2023). "The relationship between obesity and hypertension is complex and multifactorial, involving genetics, environment, sympathetic nervous system activity, renal function, and insulin resistance." (PMID 37735642, 2023). "These high insulin levels can promote the storage of excess glucose as fat, leading to weight gain and obesity." (PMID 37600709, 2023). "As in other jurisdictions, child overweight and obesity is a major problem in the Irish population potentially increasing pressure on pancreatic insulin production." (PMID 37550598, 2023). "High insulin levels led to decreased lipid utilization, which will increase the lipid accumulation and aggravate obesity and hyperlipidemia." (PMID 36986059, 2023). "They modulate the expression of insulin and adipokines through cannabinoid receptors, and their levels are known to be elevated in states of hyperglycemia and obesity." (PMID 37513500, 2023). "Some studies show an association between these AP drugs and cardiovascular effects, resistance to insulin, obesity, and dyslipidemia." (PMID 37876624, 2023). "Three mechanisms are mainly used to explain the relationship between obesity and cancer: sex hormone impaired metabolism, impaired insulin signaling and an excess of pro-inflammatory cytokines." (PMID 37686769, 2023). "In early-onset obesity, miR-3075 is released via exosomes from hepatocytes and mediates enhanced insulin sensitivity." (PMID 36902339, 2023). "circGlis3 overexpression enhances insulin secretion and inhibits obesity-induced apoptosis in vitro and in vivo." (PMID 36681689, 2023). "To better understand the effect of aging in the skin of chow, HFD and HFD DM+ mice, we screened three different gene arrays: Aging, Insulin Pathway and Obesity." (PMID 36800369, 2023). "During the first visit to the center, higher HDL concentrations were observed in the group of children with overweight, and higher HOMA IR, triglyceride, and insulin levels were noted in children with obesity." (PMID 37892696, 2023). "Obesity-related accumulation of BCAA in plasma has been reported to interfere with the insulin signaling via activation of the mammalian target of rapamycin (mTOR) pathway, precisely the complex mTOR/p70S6K, with leucine as the most potent mTOR activator." (PMID 36771236, 2023). "Muscle GR signaling alters the muscle transcriptome and the blood amino acid, glucose, and insulin levels in CORT-induced obesity." (PMID 36917179, 2023).